PALB2 (partner and localizer of BRCA2)
Diseases named in the same sentence as PALB2 in open-access papers (continued):
Sharing a sentence is not in itself a finding about the gene and the disease.
Fanconi anemia (continued). "Proteins other than BRCA2 implicated in homologous recombination or the Fanconi anemia repair pathway, like BRCA1, RAD51, PALB2, XRCC3, FANCI, or FANCD2, were at most modestly affected, as were non-homologous end joining proteins like KU80, KU70, and XRCC4." (PMID 28575672, 2017). "Although mutated PALB2 has been linked with HBOC syndrome and Fanconi Anemia, its role in the pathogenesis of PDAC has only recently been shown." (PMID 24624093, 2014). "The protein product of the Fanconi anaemia gene PALB2 (FANCN) serves as a bridge between BRCA1 and BRCA2." (PMID 23587053, 2013). "Immediately after PALB2 was discovered, evidence showed that it was also a Fanconi anemia gene, known as FANCN." (PMID 23935836, 2013). "Additionally, significant roles are played by PALB2, ATM, ATR, CHEK1, CHEK2, RAD51, and genes linked to Fanconi anaemia." (PMID 40069561, 2025). "Interestingly, germline mutation rate of members of the Fanconi anaemia family of genes (including BRCA2, PALB2, BRIP1, RAD51C, FANCA, FANCI and FANCL) was 53.4% (31/58) among the patients with germline mutations in our cohort." (PMID 32091409, 2020). "Interestingly, PALB2 (FANCN) and BRCA2 (FANCD) are involved in replication-dependant removal of interstrand DNA crosslinks associated with Fanconi anemia." (PMID 31017574, 2019). "Examples include BRIP1, PALB2, and ataxia-telangiectasia mutated (ATM) variant alleles that produce a Fanconi anemia (BRIP1 and PALB2) or ATM phenotype when inherited in biallelic fashion, but result in only moderate cancer susceptibility as a single deleterious allele." (PMID 30120226, 2018). "Together with previous data, in which PALB2 anomalies have been rarely identified in WT, with the exception of WTs arising in Fanconi anemia patients, our data suggest that this gene could play a role, if any, in a restricted fraction of sporadic WTs only." (PMID 30344923, 2018). "Monoallelic germline pathogenic variants (GPVs) in five Fanconi anemia (FA) genes (BRCA1/FANCS, BRCA2/FANCD1, PALB2/FANCN, BRIP1/FANCJ, and RAD51C/FANCO) confer an increased risk of breast (BC) and/or ovarian (OC) cancer, but the role of GPVs in 17 other FA genes remains unclear." (PMID 39149814, 2024). "Likewise, biallelic BRCA1, BRCA2, BRIP1, PALB2 and RAD51C mutations lead to Fanconi anemia." (PMID 36292468, 2022). "This pathway involves multiple proteins, including BRCA1, BRCA2, proteins of the MRN complex, CtIP, RAD51, ATM, H2AX, PALB2, RPA, RAD52, and proteins of the Fanconi anemia pathway." (PMID 38236558, 2024). "FANCM is part of the Fanconi anemia group together with BRCA2, BRIP1 and PALB2 (also known as FANCD1, FANCJ, and FANCN)." (PMID 33086730, 2020). "PALB2 (Partner and Localizer of Breast Cancer 2 (BRCA2)) plays an important role in maintaining genome integrity through its role in the Fanconi anemia (FA) and homologous recombination (HR) DNA repair pathways." (PMID 28858227, 2017). "Interestingly, however, it has been shown that biallelic, null germline mutations in BRCA2 and PALB2, hypomorphic mutations in BRCA1 and Rad51C, or in the case of RAD51 a dominant mutation, all give rise to a spectrum of clinical symptoms that have features of Fanconi Anaemia (FA)." (PMID 26990772, 2016). "A common DNA damage network between the BRCA and Fanconi anaemia (FA) pathways has been proposed and three FA genes, FANCD1, FANCN, and FANCJ, are identical to the BRCA genes BRCA2, PALB2, and BRIP1." (PMID 24550935, 2014). "Interestingly, the gene underlying the D1 subtype of Fanconi anemia, FANCD1, was found to be BRCA2 and biallelic mutations in BRCA2/FANCD1 originate a phenotype with high risk of childhood malignancies, very similar to that produced by PALB2/FANCN biallelic mutations." (PMID 23935836, 2013).
Fanconi anemia (continued). "Conversely several components within the Fanconi anemia network, interact with BRCA1 (directly or indirectly) and participate in BRCA1-dependent DNA repair of DSBs, including FANCJ (=BACH1), FANCN (=PALB2), and FANCD1 (BRCA2)." (PMID 23802008, 2013). "HRD has been observed not only in ovarian cancer patients with germline or somatic BRCA1 or BRCA2 mutations but also in those with epigenetic silencing of BRCA1 or loss of function of other genes, such as ATM, ATR, BARD, BRIP, EMSY, PALB2, RAD51, and Fanconi Anemia Complementation Group genes." (PMID 36836518, 2023). "FANCS/BRCA1, FANCD1/BRCA2, FANCN/PALB2 and FANCO/RAD51C are Fanconi anemia (FA) genes." (PMID 37566130, 2023). "Other defects in homologous recombination repair genes, such as EMSY, RAD51, ATM, ATR, Fanconi anemia, BARD1, BRIP1, PALB2, RB1, NF1, CDKN2A, and the suppression of BRCA1 transcriptional activation through gene methylation, are associated with homologous recombination deficiency (HRD)." (PMID 32679669, 2020). "This analysis identified several novel ATR synthetic lethal partner genes involved in DNA damage/repair including those targeting components of the HR/Fanconi Anaemia pathway (FANCE, SLX4, PALB2), DNA mismatch repair (MSH4, PMS2) and trans-lesion synthesis (RAD18) pathways." (PMID 27958275, 2016). "PALB2 is a partner of BRCA1/2 and is involved in Fanconi anemia." (PMID 28027327, 2016). "Among DNA repair genes, we detected a high presence of members of the Fanconi Anemia Complementation Group (FANCC, FANCD2, FANCG, FANCA, and FANCE), which participate in homologous recombination DNA repair, and genes involved in double-strand break repair (BRCA2, BRIP1, BARD, BLM, CHEK2, and PALB2)." (PMID 30487452, 2018). "These genes include the Fanconi anemia pathway genes: FANCA, PALB2, BRIP1, RAD51C and XRCC2 and non-Fanconi anemia genes: ATM, CHEK2, NBN, RAD50, RAD51B, and RAD51D." (PMID 28202063, 2017).
prostate carcinoma (72 papers, 2008 to 2025). A carcinoma that arises from epithelial cells of the prostate gland. "There is also accumulating evidence supporting a potential link between PALB2 mutations and other cancers, such as ovarian and prostate cancer, highlighting the broader clinical significance of PALB2 in hereditary cancer syndromes." (PMID 41049353, 2025). "Several studies have demonstrated the clinical benefits of PARP inhibitors for these patients, and the US FDA has approved their use for breast, ovarian, and prostate cancer patients with PALB2 or BRCA1 mutations." (PMID 38672648, 2024). "Mutations in PALB2 can impair this repair process, leading to genomic instability and an increased risk of cancer development including that of prostate cancer." (PMID 39796639, 2024). "Rucaparib, another PARPi, has also shown promise in treating prostate cancer patients with PALB2 somatic mutations with a response rate of 100% in mCRPC as seen in the phase 2 TRITON2 study." (PMID 39796639, 2024). "BRCA1 and PALB2 genetic aberrations are associated with both breast and prostate cancer predisposition." (PMID 38131903, 2023). "PALB2 mutations were associated with more aggressive forms of prostate cancer and a higher mortality rate." (PMID 37021836, 2023). "P/LP/D status aggregated across BRCA2, ATM, NBN, and PALB2 was strongly associated with risk of overall prostate cancer (OR = 4.51; 95% CI = 2.18–9.33; P = 4.75 × 10−05) and metastatic disease (OR = 6.92; 95% CI = 2.34–20.49; P = 4.76 × 10−04)." (PMID 38014910, 2023). "As previously discussed, individuals with a germline mutation in several genes (BRCA2, ATM, PALB2) are at increased risk for biochemical recurrence and prostate cancer-specific mortality." (PMID 35732815, 2022). "We tested the impact of PALB2 or BARD1 loss on olaparib and rucaparib sensitivity across prostate cancer cell lines and observed a significant increase in sensitivity in PALB2- or BARD1-depleted cells compared to control cells across the cell line models." (PMID 35768576, 2022). "Germline mutations in PALB2 are associated with increased breast and ovarian cancer risk are have also been identified in prostate cancer patients." (PMID 35768576, 2022). "Taken together, these data indicate that PALB2 or BARD1 loss in prostate cancer cells is sufficient to induce an HR-deficient phenotype." (PMID 35768576, 2022). "BRCA2-type HRD deficiencies (including BRCA2, RAD51C, PALB2 deficiencies) were more frequent in pancreatic and prostate cancer." (PMID 33149131, 2020). "Furthermore, mutations in DNA damage repair genes such as BRCA2, ATM, CHEK2, BRCA1, RAD51, and PALB2 have been implicated in familial prostate cancer." (PMID 40716035, 2025). "Finally, germline PVs in BRCA1, BRCA2, PALB2 or ATM were independently associated with short time to castration in patients with advanced prostate cancer." (PMID 37511593, 2023). "The PALB2 is associated with breast, ovarian, pancreatic, and prostate cancer." (PMID 32853479, 2020). "Notably, prostate cancer patients with PALB2 mutations receiving different PARPis have demonstrated antitumor activity." (PMID 33233320, 2020). "Observed PALB2 variants among the Finnish familial and unselected prostate cancer cases." (PMID 20003494, 2009). "However, while control (siNEG) cells form Rad51 foci indicative of HR-mediated repair, cells with siRNA-mediated depletion of PALB2 or BARD1 resemble BRCA2-deficient cells and fail to form Rad51 foci, suggesting that PALB2 or BARD1 loss is sufficient to confer HR deficiency in prostate cancer cells." (PMID 35768576, 2022). "Germline BRCA2 pathogenic variants (PVs) are known to cause ~4% of prostate cancer, but other homologous repair genes, BRCA1, ATM, PALB2 and Lynch syndrome genes are also involved." (PMID 40046829, 2025). "For instance, poly(ADP)-ribose polymerase inhibitors target DNA repair defective prostate cancer (especially BRCA2 and PALB2 biallelic loss)." (PMID 40685286, 2025).
prostate carcinoma (continued). "For example, in prostate cancer, pathogenic germline variants in DNA repair genes (ATM, CHEK2, PALB2, BRCA2) vary by ancestry; some are enriched or even unique to specific populations, leading to differences in prevalence and risk across groups." (PMID 41573212, 2025). "Recent studies have also demonstrated that a substantial proportion of pancreatic and prostate cancer patients harbor mutations in key HRR genes, notably BRCA1/2, ATM, PALB2, and CDK12." (PMID 40830526, 2025). "This clinical trial will include advanced/relapsed ovarian, breast, pancreatic, and prostate cancer patients who can be treated with PARPis and HER2-negative breast cancer patients with BRCA1/2, PALB2, RAD51C, and RAD51D mutations." (PMID 40521389, 2025). "Pathogenic mutations in cancer-driven genes like ATM, CHEK2, PALB2, and XRCC2 have been reported to increase the risk of different malignancies, especially breast and prostate cancers." (PMID 38784039, 2024). "In the current study, the set of genes (ATM, BRCA2, PALB2, and NBN) were those previously shown to be strongly associated with prostate cancer risk in this African ancestry sample." (PMID 38014910, 2023). "Among 743 Black prostate cancer patients, we identified 26 unique pathogenic (P) or likely pathogenic (LP) variants in 14 genes (including HOXB13, BRCA1/2, BRIP1, ATM, CHEK2, and PALB2) among 30 men, or approximately 4.0% of the patient population." (PMID 36446039, 2022). "Other genes implicated in the development of prostate cancer include those involved in Homologous Recombination DNA repair: BRCA1 in 199452, CHEK2 in 200353,54, ATM in 200455, and PALB2 in 200856." (PMID 35732815, 2022). "Here we use a combination of functional approaches to demonstrate that loss of PALB2 or BARD1 is sufficient to confer an HR-deficient phenotype and drive PARP inhibitor sensitivity in prostate cancer models." (PMID 35768576, 2022). "It would be logical to theorise that prostate cancers with PALB2 (partner and localiser of BRCA2) alterations would respond to PARPi similarly to BRCA2, given its role in HRR." (PMID 36497408, 2022). "PALB2 or BARD1 loss also significantly increased sensitivity to the PARP inhibitors olaparib and rucaparib across a panel of prostate cancer cell lines." (PMID 35768576, 2022). "BRCA2 variants were the most prevalent at 5.3%, and variants in ATM, CHEK2, PALB2, BRCA1, and RAD51D were also more common among men with lethal prostate cancer." (PMID 36446039, 2022). "We used functional approaches to directly test the impact of PALB2 and BARD1 loss on homologous recombination (HR) function and PARP inhibitor sensitivity in prostate cancer cell lines." (PMID 35768576, 2022). "Here, using a series of prostate cancer cell lines, we show that PALB2 or BARD1 loss is sufficient to induce an HR-deficient phenotype and sensitize prostate cancer cells to PARP inhibition." (PMID 35768576, 2022). "Conversely, DNA repair pathwaysos such as BRCA, CHEK, or PALB2 signaling is believed to affect prostate cancer development and progression." (PMID 34782700, 2021). "The patient (II-5) with PALB2 PV (c.2257C>T; p.(Arg753*)) was affected by prostate cancer at 71 years and by gastric cancer at 72 years." (PMID 34026625, 2021). "Emerging data has also linked several germline DNA mutations to prostate cancer, namely BRCA1, BRCA2, MSH, ATM, PALB2, CHEK2, and MUTYH." (PMID 32957584, 2020). "The National Comprehensive Cancer Network prostate cancer guideline recommends genetic counseling for patients with prostate cancer and having BRCA1/2, ATM, PALB2, or FANCA mutation." (PMID 31931827, 2020). "Taken together, we have shown that Andrographolide is an effective anti-cancer compound for prostate cancer by regulating genes associated to double-strand breaks such as ATM, NBN, BRCA2 BLM, PALB2 and BLM." (PMID 30800220, 2019).
prostate carcinoma (continued). "Prostate cancer patients who have mutations in the DNA repair pathway (such as BRCA1, BRCA2, ATM, RAD51D and PALB2) have been shown to be significantly more likely to have advanced disease than patients without these mutations." (PMID 31915536, 2019). "Further research is required to assess the utility of testing for PALB2 in prostate cancer." (PMID 40046829, 2025). "In breast, ovarian, pancreatic, and prostate cancers, homologous recombination (HR)–deficiency signatures were more common in tumors with new pathogenic missense mutations in BRCA1/2, PALB2, and RAD51C than in benign missense mutations (66.7% v 35.2%, P = .021)." (PMID 40570257, 2025). "Consequently, many HR deficient cases are identified by sequencing BRCA1/2 or PALB2, and this approach has led to initial approval of PARP inhibitors in multiple tumor types including breast, ovarian, pancreatic, and prostate cancer." (PMID 38589664, 2024). "We examined the aggregate association of rare germline pathogenic/likely pathogenic/deleterious (P/LP/D) variants in ATM, BRCA2, PALB2, and NBN with a polygenic risk score (PRS) on prostate cancer risk among 1,796 prostate cancer cases (222 metastatic) and 1,424 controls of African ancestry." (PMID 38014910, 2023). "Therefore, to gain additional insights regarding the role of PALB2 and BARD1 alterations on prostate tumor biology and therapy response, we modeled PALB2 and BARD1 loss in the prostate cancer cell lines DU145, LNCaP, and 22Rv1." (PMID 35768576, 2022). "Studies of families with mutations in PALB2 have not demonstrated an increased risk for prostate cancer, but PALB2 variants have been associated with aggressive prostate cancer and with metastatic prostate cancer." (PMID 35732815, 2022). "Furthermore, clinical trials undertaken with prostate cancer patients who are carriers of a mutant PALB2 have demonstrated a positive response to Olaparib treatments, particularly for patients with resistance to treatment." (PMID 36292577, 2022). "The association with a family history of prostate cancer was seen in PALB2 carriers compared with mutation negative patients." (PMID 34439348, 2021). "Germline or somatic mutations in DNA damage repair (DDR) genes, such as BRCA2, CHEK2, ATM, RAD51D, BRCA1, and PALB2, have been described in around 20–25% of advanced prostate cancer patients, which involved in aggressive disease and poor outcomes in these patients." (PMID 33413230, 2021). "Several other cancer types were detected in the 1st–3rd degree relatives of almost all BRCA1, BRCA2 and PALB2 carriers, the most common ones being stomach (in 10 families), lung (9 families), colorectal (6 families), pancreatic (6 families) and prostate cancer (5 families)." (PMID 40009290, 2025). "Although molecular alterations in HRR genes besides BRCA1/2 are less established surrogate markers for HRD, mutations in ATM and PALB2 but not in other HRR genes were shown to be associated with sensitivity to PARPi in prostate carcinoma in a phase 3 clinical trial." (PMID 36779660, 2023).